DUSP1 (dual specificity phosphatase 1)
Diseases named in the same sentence as DUSP1 in open-access papers (continued):
Sharing a sentence is not in itself a finding about the gene and the disease.
nasopharyngeal carcinoma (2 papers, 2025). A carcinoma arising from the nasopharyngeal epithelium. "Conversely, reducing FOLR1 levels alters key apoptotic and MAPK pathway genes (BIRC3, caspases, FOS, DUSP1, PRKX, TNFRSF10A), sensitizing taxol-resistant nasopharyngeal carcinoma cells to chemotherapy." (PMID 41439026, 2025). "Aloe-emodin inhibits nasopharyngeal carcinoma cell (5-8F and CNE1) proliferation, migration, and promotes apoptosis by regulating Dual specificity phosphatase 1 (DUSP1), blocking ERK-1/2, AKT, and p38-MAPK pathways, and stabilizing DUSP1 via ubiquitin–proteasome inhibition." (PMID 40490812, 2025).
pneumonia (2 papers, 2024). An acute, acute and chronic, or chronic inflammation focally or diffusely affecting the lung parenchyma, caused by an infection in one or both of the lungs (by bacteria, viruses, fungi, or mycoplasma.). "TNF‐neutralizing antibody reduced Dusp1 and Ptprs levels in AM from aged mice and reduced pneumonia severity following bacterial challenge." (PMID 38459711, 2024).
renal carcinoma (2 papers, 2022 to 2023). A carcinoma arising from the epithelium of the renal parenchyma or the renal pelvis. "In vitro experiments, we found that DUSP1 knockdown significantly promoted the proliferation, migration, and invasion of renal carcinoma cells." (PMID 37503331, 2023). "To validate our results in clinical specimens, we used immunohistochemistry and semi-quantitative analyses, which showed that compared with adjacent tissues of renal cancer, FOSB and DUSP1 were down-regulated in the glomerulus of IgAN patients." (PMID 35910761, 2022).
sarcoma (2 papers, 2025). A usually aggressive malignant neoplasm of the soft tissue or bone. "Among the DUSPs inhibitors that have demonstrated a good antitumour efficacy, BCI, a benzoil-derivative small-molecule inhibitor of DUSP1 and DUSP6, has been reported to reduce BC, MPNST, LUAD, GC and sarcoma growth." (PMID 40943262, 2025).
tauopathies (2 papers, 2016 to 2023). "We found that deficits of DUSP1 expression introduced signs of tauopathy and synaptopathy in pyramidal neurons of mouse cortex." (PMID 27849045, 2016). "Multiple members of this module (FOS, DUSP1) were previously found to be upregulated via bulk measurements of both PBMCs and hippocampus in AD, suggesting consistent dysregulation of AP-1 transcription factor genes in both primary and secondary tauopathies." (PMID 37464408, 2023).
triple-negative breast carcinoma (2 papers, 2017 to 2020). An invasive breast carcinoma which is negative for expression of estrogen receptor (ER), progesterone receptor (PR), and human epidermal growth factor receptor 2 (HER2). "DUSP1 methylation was significantly associated with ER/PR-negative status; in particular, triple-negative breast cancer patients showed the highest frequency of DUSP1 methylation in both tumour DNA and PBL DNA." (PMID 28220843, 2017).
Achalasia (1 paper, 2023). A disorder of esophageal motility characterized by the inability of the lower esophageal sphincter to relax during swallowing and by inadequate or lacking peristalsis in the lower half of the body of the esophagus. "Analysis of DEGs showed the upregulations of PPDPF, NENF, and CYBA and downregulations of FOS, DUSP1, and GPX1 in peripheral blood myeloid cells of achalasia." (PMID 37542039, 2023).
alcohol (1 paper, 2023). "Thus, based on bioinformatics analysis predicting the interaction between DUSP1 and CUL1, the task of our present research was to figure out whether DUSP1 protects the liver against alcohol-related injury through preventing CUL1-mediated mitophagy suppression." (PMID 37063418, 2023).
anxiety depression (1 paper, 2024). "Six core mRNAs on which ZZCD works for anxiety depression were obtained by constructing PPI network: Fos, Junb, Egr2, Dusp1, Nr4a1, and Btg2." (PMID 37905694, 2024).
artery disease (1 paper, 2021). "In contrary artery disease—a condition associated with EndMT1,26—the reciprocity between MAPK7 and EZH2 is disturbed, resulting in elevated expression of DUSP-1 and EZH2 and the decreased expression of MAPK7." (PMID 34493753, 2021).
ataxia telangiectasia (1 paper, 2019). Ataxia-telangiectasia is the association of severe combined immunodeficiency (affecting mainly the humoral immune response) with progressive cerebellar ataxia. "On the other hand, p38 MAPK, another NRF2-inhibitory kinase, was indeed switched-off in Ataxia Telangiectasia cells by Dexamethasone-mediated induction of DUSP1 phosphatase, and therefore it appeared that it might account for NRF2 triggering." (PMID 31107893, 2019).
autoimmune encephalitis (1 paper, 2019). Inflammation of the brain secondary to an immune response triggered by the body itself. "In contrast, mice lacking DUSP1/MKP-1 were protected from experimentally induced autoimmune encephalitis (EAE) following injection of myelin oligodendrocyte glycoprotein peptide (MOG35–55)." (PMID 30401534, 2019).
autoimmune thyroid disease (1 paper, 2025). Inflammatory disease of the thyroid gland due to autoimmune responses leading to lymphocytic infiltration of the gland. "Increased IL-10 expression has been reported in autoimmune thyroid diseases, suggesting that anti-inflammatory responses may occur simultaneously via IL10RB, DUSP1, DUSP2, and RGS1 in GD." (PMID 40710355, 2025).
Autoimmunity (1 paper, 2011). The occurrence of an immune reaction against the organism's own cells or tissues. "Interestingly, both DUSP1 (dual specificity phosphatase 1) and COX2 are known regulators of inflammatory responses and both have been associated with autoimmunity." (PMID 21961521, 2011).
bacterial pneumonia (1 paper, 2024). Acute infection of the lung parenchyma caused by bacteria (e.g., Streptococcus pneumoniae, Haemophilus influenzae, Chlamydia pneumoniae, Mycoplasma pneumoniae, and Legionella pneumophila). "We conclude that chronic exposure to TNF increases the expression of the glucocorticoid‐associated MAPK signaling suppressors, Dusp1 and Ptprs, which inhibits AM activation and increases susceptibility to bacterial pneumonia in older adults." (PMID 38459711, 2024).
behavioral disorders (1 paper, 2025). "Notably, genes associated with immune modulation and inflammation (e.g., Dusp1, Lrrc39, E2f2), neuroplasticity and memory (e.g., Cpeb3, Efnb3), and behavioral disorders (e.g., Pla2g4c) exhibited substantial changes." (PMID 40285614, 2025).
bipolar disorder (1 paper, 2019). A disorder of the brain that causes unusual shifts in mood, energy, activity levels and the ability to carry out day-to-day tasks. "DUSP6 and DUSP1 gains of function behave as markers of the progression and prognosis of bipolar disorder and depressive behavior, respectively, and they are responsible for deficient ERK signaling in these pathologies." (PMID 31018603, 2019).
Bladder tumor (1 paper, 2023). "The opposite situation is observed in the bladder tumor, where an increase in DUSP1 levels in M2-like OAMs is noted." (PMID 38139370, 2023). "Bladder tumor cells may affect the polarization of macrophages towards M2, an effect that can be inhibited through the upregulation of DUSP1 by stimulating DUSP1 transcription using the long non-coding RNA LINC00702." (PMID 38139370, 2023).
bone cancer (1 paper, 2022). A primary or metastatic malignant neoplasm affecting the bone or articular cartilage. "A dual-specificity protein phosphatase 1 (DUSP1) that functions as a negative regulator of MAPK family members, and is known to be up-regulated in bone cancer, is another target proposed for the natural product." (PMID 35956961, 2022).
brucellosis (1 paper, 2024). Brucellosis is a bacterial infection that spreads from animals to people via unpasteurized dairy products or by exposure to contaminated animal products or infected animals. "Interestingly, a series of commonly upregulated genes were identified in brucellosis patients, with seven genes/transcription factors (RGS1, DUSP1, FOS, PPP1R15A, TNFAIP3, HLA‐E, and ZFP36) being the most frequent (nine times among nine clusters)." (PMID 39135683, 2024).
Cachexia (1 paper, 2022). Severe weight loss, wasting of muscle, loss of appetite, and general debility related to a chronic disease. "A correlation matrix illustrated the correlation between cachexia-related clinical-pathological characteristics and DUSP1 expression across all patients." (PMID 36387242, 2022). "In fact, our study found several intriguing correlations between cachexia-related characteristics and DUSP1 expression, providing suggestion that it has functional relevance in vivo." (PMID 36387242, 2022). "DUSP1 protein and mRNA levels were increased significantly in skeletal muscle tissues from patients with cancer cachexia." (PMID 36387242, 2022). "Furthermore, cellular functions and clinical significance of DUSP1 in cachexia were investigated." (PMID 36387242, 2022). "Patients with cachexia had higher levels of DUSP1 expression in their myofibers compared to patients without cachexia, according to representative images of IHC (p<0.05)." (PMID 36387242, 2022).
cataract (1 paper, 2015). Partial or complete opacity of the crystalline lens of one or both eyes that decreases visual acuity and eventually results in blindness. "CCL2, DUSP1, FAS and transcription factor c-Jun may be used as specific therapeutic molecular targets in order to treat cataracts induced by GCs." (PMID 25672806, 2015).
chlamydial infection (1 paper, 2023). "Utilizing DUSP1(−/−) mice, Rodriguez and others demonstrated that DUSP1 is an essential negative regulator of TLR-triggered innate immune activation in chlamydial infection promoting chlamydial growth through direct effects on infected cells." (PMID 38149246, 2023).
chronic hepatitis C (1 paper, 2015). "The expression levels of a subset of eight genes, including dual specificity phosphatase 1 (DUSP1) and ubiquitin-specific protease 18 (USP18), have previously been used to predict the treatment response of patients with chronic hepatitis C." (PMID 25798824, 2015).
chronic myeloid leukemias (1 paper, 2019). "Finally, a recent paper has implicated DUSP1/MKP-1 in a growth factor-dependent pathway, which promotes intrinsic resistance to the tyrosine kinase inhibitors (TKI) used to treat chronic myeloid leukemias (CML)." (PMID 30401534, 2019).
Duchenne muscular dystrophy (1 paper, 2019). Duchenne muscular dystrophy (DMD) is a neuromuscular disease characterized by rapidly progressive muscle weakness and wasting due to degeneration of skeletal, smooth and cardiac muscle. "DUSP1/MKP-1 has also been implicated in muscle regeneration as DUSP1−/− mice are impaired in their ability to recover from experimental muscle injury and, when crossed into a mouse model of Duchenne's muscular dystrophy (the mdx dystrophin null), they display exacerbated muscular dystrophinopathy." (PMID 30401534, 2019).
Glomerular sclerosis (1 paper, 2025). Accumulation of scar tissue within the glomerulus. "Patients exhibiting low DUSP1 expression levels presented with higher 24-h urinary protein excretion, reduced eGFR, and more pronounced glomerular sclerosis and interstitial fibrosis on renal biopsy." (PMID 40852352, 2025).
glomerulonephritis (1 paper, 2022). A renal disorder characterized by damage in the glomeruli. "Alternatively, for glomerulonephritis for which glucocorticoid treatment has limited efficacy, directly targeting DUSP1 may be a potential strategy to prevent tubulointerstitial injury because of its potency." (PMID 35488446, 2022). "In our study, the expression of DUSP1 was generally reduced in various types of glomerulonephritis, which may promote upregulation of the MAP kinase pathway and related inflammatory signalling." (PMID 35488446, 2022). "Thus, the results of our study support future studies to test the efficacy of targeting DUSP1 in various glomerulonephritis and researchers may particularly focus on the validation of the benefits of DUSP1 restoration by in vivo experiments." (PMID 35488446, 2022).
hepatitis C infection (1 paper, 2019). "Thus, the effects of DUSP1 knock down on the interferon response to hepatitis C infection may be indirect effects of increased MAPK activation (Section 2.1) rather than direct inactivation by DUSP1." (PMID 30764493, 2019).
inflammatory breast carcinoma (1 paper, 2012). An advanced, invasive breast adenocarcinoma characterized by the presence of distinct changes in the overlying skin. "A similar discussion could be relevant on molecular profiling of inflammatory breast cancer, where DUSP1 was also among the genes suggested to be useful diagnostic and prognostic markers." (PMID 23227362, 2012).
kidney injury (1 paper, 2024). Trauma to the kidney. "Second, it remains unknown how acute kidney injury downregulates DUSP1 in the myocardium." (PMID 38322592, 2024).
leiomyoma (1 paper, 2014). A well-circumscribed benign smooth muscle neoplasm characterized by the presence of spindle cells with cigar-shaped nuclei, interlacing fascicles, and a whorled pattern. "DUSP1, IGFBP6 and NEDD9 were down-regulated in the majority of leiomyomas compare to matched normal tissues in accordance with microarray data." (PMID 25268745, 2014). "It is plausible that MAPK signaling may be activated in leiomyomas because of the decreased inhibition by DUSP1, and lncRNAs might be involved in the regulation of MAPK signaling through DUSP1." (PMID 25268745, 2014).
liver diseases (1 paper, 2023). "Several studies highlighted a close relationship between DUSP1 and liver diseases." (PMID 37063418, 2023).
lymphoma (1 paper, 2018). A malignant (clonal) proliferation of B- lymphocytes or T- lymphocytes which involves the lymph nodes, bone marrow and/or extranodal sites. "Here again, expression of cFOS, MXD1, JUNB, cJUN, and DUSP1 was significantly higher (3.7 fold, 7.1 fold, 3.1 fold, 3.4 fold and 9.1 fold, respectively) in lymphomas with high cytoplasmic NR4A1 content (p < 0.036)." (PMID 30266952, 2018).
malignant peripheral nerve sheath tumor (1 paper, 2023). Malignant peripheral nerve sheath tumor (MPNST) is a rare and often aggressive soft tissue sarcoma occurring in a wide range of anatomical sites. "In several types of cancers such as pre-B acute lymphoblastic leukemia (ALL) or malignant peripheral nerve sheath tumor (MPNST) where DUSP1/6 upregulation is observed, genetic or drug inhibition suppresses tumor growth." (PMID 37760412, 2023).
meningioma (1 paper, 2022). A generally slow growing tumor attached to the dura mater. "It is reported that DUSP1 is a novel therapeutic target for meningioma patients and that the inhibition of DUSP1 suppresses the tumour growth in vivo." (PMID 35911442, 2022).
minimal change disease (1 paper, 2022). "Second, the protein expression level of DUSP1 in samples from patients with minimal change disease was not significantly different from that in samples from controls as assessed by immunohistochemical staining, although the RNA‐seq profiles showed prominently lower DUSP1 mRNA expression levels." (PMID 35488446, 2022).
mucinous adenocarcinoma (1 paper, 2019). An invasive adenocarcinoma composed of malignant glandular cells which contain intracytoplasmic mucin. "PAX8 and C-KIT were upregulated in most tumor types, while CKAP4 and DUSP1 were upregulated only in serous and mucinous adenocarcinoma." (PMID 31159852, 2019).
myelodysplastic syndrome (1 paper, 2025). A clonal hematopoietic disorder characterized by dysplasia and ineffective hematopoiesis in one or more of the hematopoietic cell lines. "Cytarabine is used to treat high-risk myelodysplastic syndromes (MDSs), and a report suggests that the inhibition of Nrf2 by luteolin or lentiviral shRNA enhanced the efficacy of cytarabine by decreasing levels of Nrf2-targeted DUSP1 protein in myelodysplastic syndrome patients." (PMID 41158869, 2025).
myocarditis (1 paper, 2025). Myocarditis is a condition that is characterized by inflammation of the heart muscle (myocardium). "Moreover, we have identified that DJ-1 overexpression and the gene overexpression of Dusp1 can inhibit apoptosis, subsequently ameliorating myocarditis due to the DJ-1 deficiency." (PMID 41315188, 2025). "This suggests that DJ-1 may exert its anti-apoptotic effect through downregulating Dusp1, contributing to the alleviation of myocarditis." (PMID 41315188, 2025).
nasal polyp (1 paper, 2016). "Interestingly, the level of TSLP enhancement between the control and the DUSP-1 knock-down strain was comparable to that between nasal polyp and healthy control epithelium." (PMID 27050744, 2016).
neurofibromatosis type 1 (1 paper, 2021). A clinically heterogeneous, neurocutaneous genetic disorder characterized by cafe-au-lait spots, iris Lisch nodules, axillary and inguinal freckling, and multiple neurofibromas. "In neurofibromatosis Type-I and nerve tumors, activation of DUSP1 suppressed cell proliferation." (PMID 34831059, 2021).
parasite infections (1 paper, 2013). "DUSP1 plays an important role in the negative regulation of MAPKs upon different stimuli, including bacteria and parasite infections." (PMID 24244156, 2013).
peritonitis (1 paper, 2019). Inflammation of the peritoneum (tissue that lines the abdominal wall and covers most of the organs in the abdomen). "Over-production of IL-10 in Dusp1−/− mice was observed in peritonitis models after lipopolysaccharide (LPS) challenge or infection with Escherichia coli or Staphylococcus aureus, and LPS-treated Dusp1−/− macrophages." (PMID 31316508, 2019).
pneumococcal infection (1 paper, 2024). Infections with bacteria of the species streptococcus pneumoniae. "Targeting the negative regulators, Dusp1 and Ptprs may prove not to be a viable treatment for aging individuals with pneumococcal infections as they are needed to restrain excessive inflammation, and instead, the focus should be on reducing the root cause of excessive inflammation." (PMID 38459711, 2024).
polyp (1 paper, 2016). A usually exophytic mass attached to the underlying tissue by a broad base or a thin stalk. "DUSP-1 baseline expression is almost three fold lower (p < 0.05) in polyp-derived epithelium than in healthy epithelium (0.00079 vs. 0.00195)." (PMID 27050744, 2016). "In the present study, we show that the baseline DUSP-1 levels are lower in polyp epithelium than in healthy control group and that this may contribute to reduced polyp epithelial cell capability of tuning the viral-induced pro-Th2 inflammatory responses down." (PMID 27050744, 2016). "This enhanced induction of TSLP may be a consequence of a down-regulated expression of DUSP-1 in polyp epithelium." (PMID 27050744, 2016).
polyposis (1 paper, 2016). "In conclusion, we have shown that poly(I:C)-induces expression of TSLP in primary nasal epithelial cells from polyposis patients only and that a deregulation of the expression of the DUSP-1 transcription factor may play a role in this process." (PMID 27050744, 2016).
Right ventricular hypertrophy (1 paper, 2024). In this case the right ventricle is more muscular than normal, causing a characteristic boot-shaped (coeur-en-sabot) appearance as seen on anterior- posterior chest x-rays. "Furthermore, the CIH+Dusp1−/− group exhibited notably elevated RVSP and an increased Fulton index, indicating a pronounced development of right ventricular hypertrophy." (PMID 39472573, 2024).
scrapie (1 paper, 2025). A fatal disease of the nervous system in sheep and goats, characterized by pruritus, debility, and locomotor incoordination. "In the present study, all target genes except for DUSP1 were found to be significantly downregulated in naturally affected scrapie sheep compared with healthy sheep, which is consistent with miRNA regulation." (PMID 40597437, 2025).